SHCBP1 (SHC binding and spindle associated 1)
Diseases named in the same sentence as SHCBP1 in open-access papers (continued):
Sharing a sentence is not in itself a finding about the gene and the disease.
glioma (10 papers, 2019 to 2025). A benign or malignant brain and spinal cord tumor that arises from glial cells (astrocytes, oligodendrocytes, ependymal cells). "In glioma, higher SHCBP1 expression was linked to elevated VEGFC levels, and functional enrichment analysis revealed participation in NF-κB–regulated pro-angiogenic gene networks." (PMID 41009347, 2025). "SHCBP1 is a known risk factor for glioma, suggesting the importance of continuous monitoring of patients with PTSD to mitigate potential cancer comorbidities." (PMID 40102990, 2025). "In glioma, elevated SHCBP1 levels are associated with invasive gene signatures and a poorer prognosis, and its influence on NF-κB signaling further highlights its contribution to tumor spread." (PMID 41009347, 2025). "The expression of SHCBP1 was associated with lymph node metastasis in glioma, and patients with over-expressed SHCBP1 had a poor prognosis." (PMID 36920183, 2023). "We used glioma lncRNA and mRNA databases to analyze the role of SHCBP1 and CEP55 in glioma and their associations with prognosis." (PMID 32351983, 2020). "In glioma, miR-429 has been validated as a post-transcriptional regulator by binding to the 3′ untranslated region of SHCBP1 mRNA, resulting in translational repression or mRNA decay." (PMID 41009347, 2025). "SHCBP1 is highly expressed in gliomas and promotes proliferation and invasion of glioma cells by activating the NF‐κB signalling pathway." (PMID 33423377, 2021). "We further analyzed CEP55 and SHCBP1 expression in gliomas, their relationships to patient prognosis, and their enriched KEGG signaling pathways." (PMID 32351983, 2020). "In conclusion, we found that CEP55 and SHCBP1 can be used to predict the prognosis of glioma patients with high accuracy and that SHCBP1 is an independent prognostic factor for glioma patients." (PMID 32351983, 2020). "SHCBP1 is highly expressed in glioma patients, later-staged gliomas had higher SHCBP1 expression, and SHCBP1 expression levels were negatively correlated with patient survival." (PMID 32351983, 2020). "The present study demonstrated that SHCBP1 was upregulated in glioma tissues and in U87 and U251 cells." (PMID 31427569, 2019). "In this study, the endogenous expression of UPF1, Linc-00313, miR-342-3p, miR-485-5p, Zic4, and SHCBP1 in glioma tissues and cells were determined." (PMID 31427569, 2019). "In gliomas, by activating the NF-κB signaling pathway, increased expression of SHCBP1 contributed to invasion and migration." (PMID 31007608, 2019). "Accumulating evidence has demonstrated the abnormally high expression of SHCBP1 and its oncogenic role in multiple cancers, including gastric cancer, bladder cancer, lung cancer, pancreatic cancer, prostate cancer, and gliomas." (PMID 40799237, 2025). "Furthermore, CEP55 and SHCBP1 were highly expressed in gliomas, showing higher expression in higher grade cases, and high expression patients had poorer prognoses." (PMID 32351983, 2020). "Additionally, CEP55 and SHCBP1 were highly expressed in glioma specimens and showed increased expression according to the glioma grade, and outcomes of high expression patients were poor." (PMID 32351983, 2020). "Based on the bioinformatics analysis of a large number of glioma specimens, we found that PART1 and hsa-miRNA-429 could regulate SHCBP1 expression and that SHCBP1 can be used as a molecular biomarker to judge the prognosis of glioma patients." (PMID 32351983, 2020). "To determine the role of CEP55 and SHCBP1 in glioma, we performed KEGG analyses." (PMID 32351983, 2020). "In addition, SHCBP1 could regulate the biological behaviors of glioma cells by activating the MEK/ERK signaling pathway." (PMID 31427569, 2019). "In a parallel study, SHCBP1 was identified as a prognostic marker for glioma, demonstrating a strong predictive value based on the PART1–miRNA-429–SHCBP1 axis." (PMID 41009347, 2025).
glioma (continued). "Although there are reports of a relationship between SHCBP1 and CEP55 in glioma, these have only focused on their roles in the migration and invasion of glioma cells." (PMID 32351983, 2020). "In this study we found that the expression of SHCBP1 in glioma tissues and glioma cells were significantly increased compared with that in normal brain tissues and HA cells." (PMID 31427569, 2019). "Additionally, we found that SHCBP1 is low expressed in nontumor brain tissue, but as the level of glioma increases, its expression level is correspondingly increased." (PMID 32351983, 2020). "The present study demonstrated that the overexpression of SHCBP1 increased the expression of p-MEK/MEK and p-ERK/ERK, and activated the MEK/ERK signaling pathway, which promoted the proliferation, migration, and invasion of glioma cells, and inhibited their apoptosis." (PMID 31427569, 2019).
gastric cancer (8 papers, 2020 to 2025). A primary or metastatic malignant neoplasm involving the stomach. "In gastric cancer, SHCBP1 facilitates cancer cell mitosis through hyperactivation of the HER2-mediated signaling pathway." (PMID 41009347, 2025). "In gastric cancer, SHCBP1 interacts with PLK1 to enhance MISP phosphorylation, regulating trastuzumab sensitivity." (PMID 40799237, 2025). "In a separate study, Ginsenoside Rh7, a protopanaxatriol-type saponin obtained from ginseng, was found to inhibit cell proliferation, migration, and invasion by blocking SHCBP1-mediated β-catenin nuclear localization in gastric cancer." (PMID 41009347, 2025). "TFBG showed strong affinity for the PLK1 binding pocket, thereby blocking SHCBP1 and PLK1 association, which led to cancer growth inhibition and enhanced sensitivity to trastuzumab resistance in gastric cancer." (PMID 41009347, 2025). "Emerging studies have demonstrated that SHCBP1 was up-regulated in several cancers, including breast, bladder, and gastric cancer." (PMID 36920183, 2023). "Blocking HER2 activation using trastuzumab effectively abolished EGF-induced nuclear localization of SHCBP1 in gastric cancer cells." (PMID 35013128, 2022). "We knocked down the SHCBP1 expression and found that SHCBP1 depletion inhibited the cell proliferation, and sensitized the cell to trastuzumab in gastric cancer cell SNU-216 and NCI-N87." (PMID 33990570, 2021). "To further characterize the clinical importance of SHCBP1, we evaluated patient OS from the gastric cancer TMAs and public databases, respectively." (PMID 33990570, 2021). "Collectively, these findings demonstrate that the initial SHCBP1 expression significantly correlates with trastuzumab sensitivity, unraveling the clinical importance of SHCBP1 in HER2-targeted therapy for gastric cancer." (PMID 33990570, 2021). "This was also confirmed by SHCBP1 immunoblotting of tissues from eight gastric cancer patients and SHCBP1 expression analysis of a publicly available GEO dataset." (PMID 33990570, 2021). "We also revealed that blocking SHCBP1 nuclear localization rendered gastric cancer cells sensitive to trastuzumab, demonstrating that SHCBP1 nuclear localization is a downstream consequence of HER2 activation." (PMID 33990570, 2021). "We found that TFBG partly suppressed EGF-induced Shc1 and SHCBP1 dissociation, which suggested that the feedback inhibition on Shc1–SHCBP1 of TFBG is one of the reasons why TFBG sensitize gastric cancer to trastuzumab." (PMID 33990570, 2021). "Consistently, others also reported that SHCBP1 knockdown inhibited the proliferation and metastasis of gastric cancer cell MGC-803 and SGC-7901, and suppressed the proliferation and motility of esophageal squamous cell carcinoma ESCC cells." (PMID 33990570, 2021). "Supporting findings from aggressive gastric cancer clinical samples with elevated SHCBP1, knockdown of SHCBP1 in gastric cancer cells suppresses the expression of CDK1, CDK4, and cyclin D1, consistent with a block at the G1/S phase transition and reduced cell proliferation." (PMID 41009347, 2025). "Conversely, high SHCBP1 expression was associated with longer FP (P=0.022, HR=0.77 [0.62–0.96]), OS (P=0.0058, HR=0.75 [0.61–0.92]), and PPS (P=0.00055, HR=0.67 [0.53–0.82]) in gastric cancer." (PMID 36920183, 2023). "Trastuzumab combined with an SHCBP1 inhibitor may be an effective therapeutic strategy for HER2-positive gastric cancer." (PMID 33990570, 2021). "To investigate whether upregulated SHCBP1 confers trastuzumab sensitivity, we examined SHCBP1 status by IHC in 22 HER2-positive gastric cancer patients who received trastuzumab-based therapy." (PMID 33990570, 2021). "SHCBP1 was found correlating with trastuzumab sensitivity in patients who received trastuzumab-based therapy, and SHCBP1 deletion rendered gastric cancer sensitive to trastuzumab, implying that SHCBP1 contributed to trastuzumab sensitivity and was targeted therapeutically." (PMID 33990570, 2021).
gastric cancer (continued). "Consistently, IHC staining analysis of Ki-67 showed that SHCBP1 knockdown significantly enhanced trastuzumab suppression of cellular proliferation, underscoring that SHCBP1 depletion renders HER2-positive gastric cancer sensitive to trastuzumab both in vitro and in vivo." (PMID 33990570, 2021). "In here, we demonstrated a positive correlation between HER2 and SHCBP1 expression in gastric cancer, which suggested that the SHCBP1 may be involved in HER2-promoted tumorigenesis." (PMID 33990570, 2021). "Furthermore, the univariate and multivariate analyses of patients from the gastric cancer TMAs demonstrated SHCBP1 expression was an independent prognostic factor for HER2-positive gastric cancer patients." (PMID 33990570, 2021). "Consequently, the goal of this research was to explore the antitumor impacts of ginsenoside Rh7 on gastric cancer cells by focusing on its regulation of SHCBP1 expression, β-catenin translocation, and EMT regulation to provide new insights into the GC targeted treatment." (PMID 40657397, 2025). "Notably, we showed that SHCBP1 functions as a regulator of HER2-directed gastric cancer therapy." (PMID 33990570, 2021). "In addition, we also assessed the relationship between SHCBP1 and the clinicopathological characteristics of HER2-positive patients from the gastric cancer TMAs, and found a significant correlation between SHCBP1 and tumor invasion, lymph node status and tumor stage." (PMID 33990570, 2021). "In gastric cancer, after stimulation by EGF, SHCBP1 is translocated into the nucleus and binds to PLK1 to promote the phosphorylation of MISP." (PMID 40799237, 2025). "Inhibition of the SHCBP1 and PLK1 interaction sensitizes gastric cancer cells to trastuzumab treatment." (PMID 41009347, 2025). "Depletion of SHCBP1 leads to an upregulation of pro-apoptotic proteins (BAX, cleaved caspase-3, and PARP) and a decrease in anti-apoptotic BCL2 expression in gastric cancer." (PMID 41009347, 2025). "Additionally, SHCBP1’s involvement as both a diagnostic and prognostic marker is reported in a range of other cancers, including esophageal cancer, retinoblastoma, synovial sarcoma, HNSCC, ovarian cancer, and gastric cancer, all showing high correlation scores." (PMID 41009347, 2025). "Blocking the binding of SHCBP1 and PLK1 can enhance the sensitivity of gastric cancer cells to trastuzumab." (PMID 40799237, 2025). "We screened out five overlapping Shc1-binding proteins (JUP, EPHA2, RASAL2, LYN, and SHCBP1), which were positively correlated with HER2 expression and were upregulated in gastric cancer." (PMID 33990570, 2021). "We performed immunohistochemical and immunofluorescent analysis of the gastric cancer TMAs to determine the clinical relevance of SHCBP1 and HER2, demonstrating a weak to moderate correlation between HER2 and SHCBP1 expression (Spearman coefficient = 0.36)." (PMID 33990570, 2021). "We found that SHCBP1 and RASAL2 were really upregulated in HER2-positive gastric cancer." (PMID 33990570, 2021). "In conclusion, these results suggest that SHCBP1 is a downstream effector of HER2 and may contribute to the regulation of a novel oncogenic signaling axis in response to HER2 activation in gastric cancer." (PMID 33990570, 2021).
synovial sarcoma (8 papers, 2016 to 2025). "In synovial sarcoma, upregulation of SHCBP1 resulted in greater VEGF secretion by cancer cells, which enhanced HUVEC tube formation and migration in vitro." (PMID 41009347, 2025). "The involvement of SHCBP1 in TGF-β1-induced EMT is also validated in synovial sarcoma, where SHCBP1 is upregulated following TGF-β1 stimulation." (PMID 41009347, 2025). "SHCBP1 regulates synovial sarcoma and PCa cell motility and invasion in other tumors, according to previous studies." (PMID 39949984, 2025). "Overexpression of SHCBP1 can promote synovial sarcoma cell proliferation and tumorigenicity in vitro." (PMID 38021148, 2023). "A previous study proved that activating the TGF-β1/Smad signaling pathway via SHCBP1 could facilitate metastasis and result in a poor prognosis of synovial sarcoma." (PMID 37065471, 2023). "Interestingly, Oroxylin A, a flavonoid, was found to inhibit SHCBP1 expression in synovial sarcoma cells, affecting the activity of the NF-κB signaling pathway and regulating the expression of inflammatory factors that have an inhibitory effect on tumor cell proliferation." (PMID 38005336, 2023). "SHCBP1 expression is abnormally elevated in synovial sarcoma (SS), which promotes the metastasis of SS and regulates cell proliferation through the TGF-β1/Smad signaling pathway." (PMID 38005336, 2023). "For synovial sarcoma, the specific SS18-SSX1 fusion oncoprotein has been shown to contribute to increased SHCBP1 expression, yet the molecular details are not completely defined." (PMID 41009347, 2025).
bladder cancer (7 papers, 2021 to 2025). "In bladder cancer, SHCBP1 augments EGF-induced invasive behavior by associating with RACGAP1 and restricting the GTP hydrolysis activity of RAC1, a critical regulator of actin cytoskeleton dynamics and cell motility." (PMID 41009347, 2025). "In bladder cancer, nuclear translocation of SHCBP1 induced by EGF inhibits RACGAP1-mediated RAC1 inactivation to promote cancer cell proliferation and invasiveness." (PMID 40799237, 2025). "For example, SHCBP1 enhances the migration and invasion of bladder cancer cells by inhibiting RACGAP1-mediated Rac1 inactivation." (PMID 40799237, 2025). "In the present study, we explored the clinical significance and regulatory mechanisms of SHCBP1 in bladder cancer." (PMID 35013128, 2022). "Our results showed that blockade of GTP-RAC1 using Ehop-016 inverses EGF-induced cell migration of 5637 cells expressing SHCBP1, indicating its positive effect on cell movement in bladder cancer, which is supported by other studies." (PMID 35013128, 2022). "Herein, we report that SHCBP1 is upregulated in bladder cancer tissues and cells, with cytoplasmic or nuclear localization." (PMID 35013128, 2022). "We found that SHCBP1 was upregulated in human bladder cancer tissues compared with adjacent urothelial mucosa tissues." (PMID 35013128, 2022). "RT-qPCR confirmed that RACGAP1 expression was elevated in bladder cancer tissues, and there was a significant positive correlation between SHCBP1 and RACGAP1 mRNA expression." (PMID 35013128, 2022). "The IHC results showed that SHCBP1 staining was stronger in bladder cancer tissues than in adjacent normal tissues, and SHCBP1 was observed in the cytoplasm and nucleus." (PMID 35013128, 2022). "A recent study has shown that the adaptor protein RacGAP1 inactivated GTP-bound Rac1 in bladder cancer, but the activation was inhibited by protein SHCBP1 (SHC-binding protein 1), which is a regulator of EGF (epidermal growth factor)." (PMID 35740379, 2022). "First, we found that EGF did not increase the total expression of SHCBP1 protein but increased SHCBP1 expression in the nuclei of three bladder cancer cell lines, as revealed by immunoblotting and IF." (PMID 35013128, 2022). "RT-qPCR revealed that SHCBP1 expression was significantly elevated in 20 bladder cancer tissues, compared with 20 adjacent normal tissues." (PMID 35013128, 2022). "Via this relay, SHCBP1 can inactivate Rac1 and promote bladder cancer progression." (PMID 35740379, 2022). "The SHCBP1/RACGAP1/RAC1 interaction could therefore serve as a potential candidate for designing novel targeted therapeutic strategies for bladder cancer in clinical management." (PMID 35013128, 2022). "Herein, we wondered whether SHCBP1 responds to EGF/EGFR activation through translocation to the nucleus in bladder cancer." (PMID 35013128, 2022). "We herein performed experiments to study whether SHCBP1 affects proliferation phenotype of bladder cancer cells." (PMID 35013128, 2022). "The role of SHCBP1 in proliferation of bladder cancer cells remains unclear." (PMID 35013128, 2022). "EGF stimulation increased the interaction between SHCBP1 and RACGAP1, which in turn attenuated the catalytic activity of RACGAP1 toward GTP-RAC1 in bladder cancer." (PMID 40789837, 2025). "Here, we identified an SHC1-binding protein, SHCBP1, which was overexpressed and related to poor DSS in patients with bladder cancer." (PMID 35013128, 2022). "In summary, our research has identified SHCBP1 as a new mediator of the crosstalk between EGF/EGFR signaling and RAC1 and a new mechanism mediating the progression of bladder cancer." (PMID 35013128, 2022). "In growth factor signaling, EGF-induced activation of HER2 triggers SHCBP1 phosphorylation at Ser273, which is essential for its subsequent nuclear import and for the activation of downstream targets including PLK1 in gastric and bladder cancer cells." (PMID 41009347, 2025).
bladder cancer (continued). "Moreover, the knockout of SHCBP1 reduced the migration and invasion ability in EGF-induced bladder cancer cells." (PMID 36920183, 2023). "Importantly, translocation of SHCBP1 to the nucleus induced by EGF treatment promoted the cell migration and invasiveness of bladder cancer cells in vitro and in vivo." (PMID 35013128, 2022). "Depletion of SHCBP1 reduces EGF-induced cell migration and invasiveness of bladder cancer cells." (PMID 35013128, 2022). "By analyzing The Cancer Genome Atlas (TCGA) dataset, we found that SHCBP1 expression was predominantly upregulated in bladder cancer samples as compared with corresponding nontumor tissues." (PMID 35013128, 2022). "However, the role of SHCBP1 in the progression of bladder cancer has not been reported." (PMID 35013128, 2022). "In this study, we found that cell movement is RAC1-dependent in bladder cancer, and RAC1 activity, but not RhoA and CDC42, is inhibited by RACGAP1, which is partially reversed following SHCBP1 ectopic expression." (PMID 35013128, 2022).
hepatocellular carcinoma (7 papers, 2014 to 2025). A malignant tumor that arises from hepatocytes. "These included that SHCBP1 knockdown prevented the cell proliferation of hepatocellular carcinoma (HCC) and induced G0/G1 arrest by downregulating p-ERK1/2 and cyclin D1 expression, emphasizing its involvement in MEK/ERK signaling." (PMID 40657397, 2025). "Additionally, SHCBP1 was demonstrated significantly overexpressed in human hepatocellular carcinomas (HCC), and the proliferation and colony formation of HCC cells were markedly reduced after SHCBP1 inhibition." (PMID 27572315, 2016). "SHCBP1 was also found to be upregulated in human hepatocellular carcinoma (HCC) samples, and knockdown of SHCBP1 in HCC cell lines reduced cell proliferation and colony formation." (PMID 25153088, 2014).